CTLA4 (cytotoxic T-lymphocyte associated protein 4)
Diseases named in the same sentence as CTLA4 in open-access papers (continued):
Sharing a sentence is not in itself a finding about the gene and the disease.
cancer (continued). "Checkpoint blockade therapies targeting CTLA-4 and PD-1/PD-L1 are successfully used as cancer immunotherapy." (PMID 33679726, 2020). "In fact, we have presented data of individual data points in most figures to highlight the fact there are patients in most cancer types with features that are favorable for anti-CTLA-4 therapy." (PMID 31991588, 2020). "The intensive study of PD-1- and CTLA-4-mediated immunosuppression culminated in the dramatic success of cancer immunotherapies and many clinical trials of ICI mono- and combination therapies targeting PD-1/PD-L1 and CTLA-4 in HCC have now been conducted." (PMID 32218257, 2020). "If this can be extrapolated to human cancer, then it is likely that depletion of CTLA-4-expressing cells will be limited to activated Treg in human cancer." (PMID 31991588, 2020). "Ipilimumab, a monoclonal antibody to cytotoxic T-lymphocyte antigen 4 (CTLA-4), blocks the effects of this regulator and increases T-cell responses against cancer cells, thus promoting increased immune system performance." (PMID 32911759, 2020). "Clinical trials in other cancers have shown synergy when both PD-1 and CTLA-4 are blocked simultaneously, however, with concomitant increases in toxicity." (PMID 33008010, 2020). "Given the large number of failures in previous trials, an important issue is which cancers are suitable indications for the next generation of anti-CTLA-4 antibodies." (PMID 31991588, 2020). "The therapeutic approach of using antibodies to block CTLA4 has been used in many cancer types and demonstrated unprecedented efficacy." (PMID 33603736, 2020). "In pre-clinical settings, the combined IT of agonistic anti-CD137 antibodies with anti-PD1 or -CTLA-4 antibodies have brought positive outcomes for distinct cancer types." (PMID 32349284, 2020). "For example, PD-L1 and CTLA-4 are well-characterized immune checkpoint inhibitors that are overexpressed in many cancer cells and promote immune escape." (PMID 32295072, 2020). "With the advent of emerging immunotherapy, the combination of immune checkpoint blockade (ICB) and local RT has produced welcome changes in stubborn metastases, especially anti-PD-1/PD-L1 and anti-CTLA-4 which have been approved in clinical cancer treatment." (PMID 32992835, 2020). "Immune-competent subtypes in 7 cancers had increased expression of these genes compared to immune-deficient subtypes except PD-1 expression in GBM and PD-L1 in PCPG, and CTLA4 in SARC." (PMID 32533054, 2020). "Immune checkpoint inhibitors (ICIs), such as PD-1/PD-L1 antibodies (Abs) and anti-cytotoxic T lymphocyte antigen 4 (CTLA-4) Abs, are effective for patients with various cancers." (PMID 32359357, 2020). "ICIs were popularly used in cancer patients to improve prognosis, especially PD‐1, PD‐L1, and CTLA‐4 antibodies." (PMID 33098370, 2020). "Combination therapy with immune checkpoint inhibitors including anti–PD-1 and –CTLA4 antibodies shows greater therapeutic efficacy than the monotherapies in several cancers." (PMID 33072070, 2020). "Historically speaking, Dr. James P. Allison first showed that the CTLA-4 blockade is effective in the murine model of cancer immunotherapy." (PMID 32492969, 2020). "Our analyses of five attributes of responsiveness to anti-CTLA-4 therapy allowed us to rank the 22 major human cancers based on individual attributes." (PMID 31991588, 2020). "CTLA-4 has an essential function in controlling the immune responses in cancer and is contemplated as a prospective target against cancer." (PMID 33324546, 2020). "Despite dramatic outcomes by the immunotherapy in some cancer patients, treatments with CTLA-4 or PD-1/PD-L1 immune checkpoint blockers were effective only in about 15% to 25% of patients with various cancers." (PMID 32847045, 2020). "Antibodies targeting other inhibitory checkpoints, such as PD-1 or CTLA4 have also driven significant improvements after vector delivery in murine cancer models." (PMID 32295072, 2020).
cancer (continued). "The relationship between gastrointestinal (GI) bacteria and the response to anti-CTLA-4 and anti-PD-1 immunotherapy in the treatment of cancer can potentially be enhanced to allow patients to maximally respond to these treatments." (PMID 32944086, 2020). "CTLA-4-blocking antibodies have been successfully trialled in murine cancer models, and are currently being implemented against human tumors." (PMID 32640575, 2020). "A case study was conducted on two cancer patients with metastatic melanoma, both treated with anti-PD-1 and anti-CTLA4 in combination." (PMID 32785162, 2020). "In cancer treatment, inhibiting immune checkpoint mediators, such as CTLA-4 and PD-1, has achieved noteworthy clinical outcomes in several malignancies." (PMID 33031059, 2020). "The immune checkpoint molecules PD-1 and CTLA-4 treatment is a promising cancer immunotherapy approach for clinical benefits." (PMID 32143735, 2020). "This inhibits CTLA-4 activation, which renders cytotoxic T lymphocytes capable of recognizing and destroying cancer cells." (PMID 33276556, 2020). "Antibodies against PD-L1 and CTLA-4 have proven effective to treat some cancers in clinical trials by blocking the immunosuppressive interaction with their receptors expressed on immune cells." (PMID 32295072, 2020). "CIBERSORT was used to determine immunocyte profiles in all TCGA patients, and the correlation between 22 immunocytes and PD-1/CTLA4 expression was determined for the 33 cancer types in TCGA." (PMID 33072070, 2020). "A number of inhibitory immunoreceptors have been identified and studied in cancer in past decades, including but not limited to PD-1, CTLA-4, LAG3, TIM3, TIGIT and BTLA." (PMID 32467592, 2020). "Recently, CTLA-4 recycling is considered to be an important factor for preventing immune-related adverse events (irAEs) during the use of anti-CTLA-4 monoclonal antibodies (mAbs) in cancer." (PMID 33121189, 2020). "Preclinical studies have shown that the inhibition of CTLA-4 can enhance therapeutic immunity to cancer." (PMID 33324546, 2020). "As expected, the master regulator IKZF1 overexpression led to enhanced immune infiltrate recruitment and tumor sensitivity to PD-1 and CTLA-4 inhibitors in cancers that typically lack IKZF1 expression." (PMID 33291616, 2020). "Ipilimumab is the first and only FDA-approved CTLA-4 inhibitor, given its ability to modualte the immune system to attack melanoma cancer cells." (PMID 32245016, 2020). "The clones enriched in the anti-PD-1 treatment also tended to be enriched in anti-CTLA-4 treatment, suggesting shared cancer cell-intrinsic ICB-resistance mechanisms for the two regimens." (PMID 33059736, 2020). "Up to now, seven drugs targeting CTLA-4/PD-1 have been approved for treatment of different types of cancer, including melanomas, lung, breast, cervical, and liver cancer." (PMID 32620130, 2020). "Despite the limited sample size, all components of 4/5 features of the cancer responsiveness ranking have been identified using this database, including CTLA4 expression, signature genes, immune cell infiltration, and mutation/Neoantigens." (PMID 31991588, 2020). "Currently, anti-CTLA-4 antibodies such as ipilimumab have shown to provide a survival benefit in cancer patients." (PMID 32760139, 2020). "The development of checkpoint blockade therapy (treatment with antibodies to block ligand binding to CTLA-4 and PD-1 receptors) has indeed revolutionised cancer treatment and patient outcomes." (PMID 33371448, 2020). "We therefore ranked 22 human cancer types based on RNAseq data from 7279 independent human cancer samples using the CTLA4 expression value." (PMID 31991588, 2020). "Sarcoidosis has been reported in patients with cancer treated with ipilimumab (anti-CTLA4 antibody)." (PMID 32486493, 2020).
cancer (continued). "The strengths of our study are the size of the real-world dual-centre cohort, the fact that it includes data from inpatients and outpatients, both CTLA-4 and PD-1 inhibitors, and patients with various cancer types." (PMID 32418993, 2020). "In cancer however, CTLA-4 halts the activation and proliferation of activated T cells that are of great value in recognizing cancer antigens." (PMID 33374927, 2020). "Frequency of genetic variants of CTLA-4, PDCD1, PD-L1, BTLA, HAVCR2, and LAG3 genes (in different human populations) for which the association with cancer risk has been investigated." (PMID 33519815, 2020). "Here we develop a strategy that integrates previous experience with Ipilimumab with genomic and expression profiles of major human cancers in order to rank cancer indications for their likely response to the next generation of anti-CTLA-4 antibodies." (PMID 31991588, 2020). "Immune checkpoint inhibitors (ICIs) targeting immune checkpoint proteins, such as CTLA-4 and PD-1/PD-L1, have demonstrated remarkable and durable clinical responses in various cancer types." (PMID 32775303, 2020). "The successful clinical application of monoclonal antibodies (mAbs) against checkpoint regulators like PD1/PD-L1 and CTLA-4 has transformed the field of cancer immunotherapy; however, their effect on iNKT cells remains to be fully elucidated." (PMID 32560408, 2020). "CTLA4 inhibitors reverse inhibitory immune signal and restore the anti-cancer response by blocking the interaction between CTLA4 and the ligand expressed by antigen presenting cells." (PMID 33117084, 2020). "Subgroup analyses showed significant differences in risk of grade 3 or higher adverse events between treatment types (PD-1 + CTLA-4 and PD-L1 + CTLA-4), among cancer types, and among dosing regimens (N1I3, N3I1, and D20T1)." (PMID 32257944, 2020). "The combination of anti-CTLA-4 and anti-PD-1/PD-L1 antibodies has shown augmented efficacy versus monotherapy in several cancers, but mainly in those that are known to have responded to anti-PD-1/PD-L1 antibodies as a single agent." (PMID 32245497, 2020). "In our study, we found that the antibody-mediated blockage of CTLA4 induced an activated T cell profile in hyperlipidemic mice, which is similar to the observations in cancer patients who receive the αCTLA4 antibody ipilimumab." (PMID 32872393, 2020). "Since the recent success of antibodies targeting checkpoint molecules CTLA-4, PD-1, and PD-L1, the field of cancer immunotherapy has been experiencing a renaissance." (PMID 32526888, 2020). "To understand the activity and mechanism of action of NKTR-214 in T-cell-based immunotherapy of cancer, we studied its use in preclinical models of PD-1 and CTLA-4 CPI therapy and in antigen-specific vaccination as well as in patient samples." (PMID 32005826, 2020). "Immune checkpoint inhibitors such as cytotoxic T lymphocyte antigen‐4 (CTLA‐4), programmed cell death protein 1 (PD‐1), and PD‐1 ligand (PD‐L1) antibodies have shown significant antitumor activity in several human cancers." (PMID 32392361, 2020). "The development of immune checkpoint blockade therapies, including anti-PD-1 and anti-CTLA4 therapies, has provided new avenues for cancer treatment." (PMID 32117733, 2020). "Immunotherapy with ICB uses monoclonal antibodies that target the inhibitory proteins CTL antigen 4 (CTLA-4) or programmed death-1/programmed death-ligand 1 (PD-1/PD-L1) on T cells or cancer cells to unleash the immune response." (PMID 33194719, 2020). "The recognition of the biological role and therapeutic potential of immune checkpoint blockade (through CTLA-4 and PD-1 targeting) has revolutionized our approach to cancer immunotherapy, as also highlighted by the 2018 Nobel Prize award." (PMID 32727102, 2020). "Immunotherapy targeting the first generation of immune checkpoint molecules (CTLA-4 and PD-1) has been proven to be effective in many cancers." (PMID 33250890, 2020).
cancer (continued). "Identification of these immunosuppressive pathways led to the development of monoclonal antibody (mAb)-based cancer therapies that inhibit PD-1/PD-L1 or CTLA-4/B7 pathways, thereby reinvigorating the host anti-tumor immune response." (PMID 32455628, 2020). "Immune checkpoint blockade therapy targeting the negative regulatory receptors CTLA-4 and/or PD-1 has transformed cancer care, being FDA approved in at least 14 distinct cancer entities." (PMID 32001684, 2020). "Here we took a comprehensive approach to rank 22 major cancer types for their responsiveness to anti-CTLA-4 antibodies." (PMID 31991588, 2020). "Due to their potent anti-cancer activity, ICIs including antibodies against PD-1 and CTLA-4 have been approved in patients with dMMR/MSI-H mCRC." (PMID 33282742, 2020). "The role of NK cells in the remarkable response of CT26 to CTLA4 blockade as well as the potential mechanism of NK activation through CD80 expressed on CT26 cancer cells remains to be elucidated by future experiments." (PMID 31898484, 2020). "Immune checkpoint blockade (ICB), including anti-PD1/PD-L1 and anti-CTLA-4 therapies has shown tremendous success in the treatment of human cancers, particularly for solid tumors." (PMID 31811337, 2020). "Blocking co-inhibitory checkpoints, such as cytotoxic T-lymphocyte-associated protein 4 (CTLA-4) and programmed cell death protein 1 (PD-1)/PD-L1, were breakthroughs in the treatment of a variety of malignant tumors." (PMID 32310827, 2020). "Immune-related adverse events, in particular autoimmunity, are among the main complications of the checkpoint-blockade cancer therapies anti-CTLA-4 and anti-PD-1." (PMID 33143070, 2020). "In this study, we addressed this question by analyzing PD-1 and CTLA4 levels in 33 different types of cancer along with their prognostic significance using The Cancer Genome Atlas (TCGA) and Cancer Cell Line Encyclopedia datasets." (PMID 33072070, 2020). "Curcumin also inhibits CSN5, diminishing PD-L1 expression in cancer cells and sensitizing cancer cells to anti-CTLA4 therapy." (PMID 32549302, 2020). "We examined the correlation between PD-1/CTLA4 levels and the degree of immune cell infiltration in diverse cancer types in TIMER." (PMID 33072070, 2020). "Antibodies targeting two immune checkpoints, PD-1 and CTLA-4, represent the greatest success of cancer immunotherapy, which can elicit durable antitumor responses in a wide range of malignancies." (PMID 32850843, 2020). "For cancer, the most promising are those that inhibit the checkpoint receptors PD-1 and CTLA-4, leading to increased antitumor T cell activity." (PMID 32665635, 2020). "Similar observations were noted in a systematic review of published literature about anti-PD1 and anti-CTLA4 antibodies used for the treatment of advanced-stage cancer in patients with HIV infection (n = 73)." (PMID 32714317, 2020). "The immune checkpoints, such as CTLA-4, PD-1/PD-L1 etc. were reported to be responsible for the immunotherapy response in many cancers." (PMID 33111959, 2020). "Monoclonal antibodies targeting CTLA-4 and PD-1/programmed cell death ligand-1 (PD-L1) axes are currently two major categories applied in cancer immunotherapies." (PMID 32306958, 2020). "Targeted manipulation of immune checkpoints, including PD-1 and CTLA-4, yields striking and durable responses in diverse cancer types, but such responses are challenging to predict." (PMID 32676589, 2020). "Cytotoxic T lymphocyte antigen 4 (CTLA4), a negative regulator of T cells leading to its inactivation, is a cancer-related immune checkpoint." (PMID 31894857, 2020). "IL-33 appears to increase the expression of PD-1/PD-L1 and CTLA-4 molecules on certain immune cells and to improve immunotherapy efficacy of checkpoint blockade in some cancer models." (PMID 33329534, 2020). "PLGA-R837/Cat-based RT plus anti-CTLA4 induced effective long-term immune memory protection against cancer recurrence, sustaining high level of TNF-α and IFN-γ." (PMID 32408880, 2020).
cancer (continued). "In particular, clinical application of immune checkpoint inhibitors, such as anti-CTLA-4 and anti-PD-1/PD-L1 antibodies, in various cancer types represents a major breakthrough in cancer therapy." (PMID 33282961, 2020). "Cancer immunotherapy consists in the administration of recombinant antibodies toward immune molecules defined as immune checkpoint (PD-1, CTLA-4), along with recombinant cytokines, oncolytic viruses, cancer vaccines, or engineered T cells." (PMID 32982967, 2020). "PD1/PDL1 and CTLA-4 have been used as immunotherapeutic targets in a number of cancer types with high expression of these genes." (PMID 32640719, 2020). "Although the clinical use of anti‐CTLA‐4 antibody and anti‐PD‐1/PD‐L1 antibody is considered to be a revolution in cancer therapy, most patients eventually relapse due to drug resistance; therefore, it is an urgent problem to discover new treatment schemes." (PMID 32077528, 2020). "Immune checkpoint inhibitors targeting CTLA-4 and PD-1, as well as neutralizing antibodies against chemokines or the corresponding receptors on Tregs, are showing promise in many cancers such as NSCLC." (PMID 32425930, 2020). "Among the therapies currently approved for clinical use are the anti-CTLA-4 mAb ipilimumab (Yervoy®), which was the first immune checkpoint inhibitor to demonstrate an anti-cancer effect, and the anti-PD-1 mAb nivolumab (Opdivo®)." (PMID 32455628, 2020). "To understand the differential effects between the CTLA-4 blockade and the PD-1 blockade in cancer immunotherapy, we first need to think about the physiological functions of CTLA-4 and PD-1." (PMID 32492969, 2020). "Recently, the immunotherapies using anti-CTLA-4 and/or anti-PD-1 monoclonal blocking antibodies have revolutionized the field of human cancer treatment." (PMID 32492969, 2020). "The queens with TN normal-like carcinomas also showed a strong positive correlation between serum PD-1 levels and serum PD-L1 (r = 0.857), CTLA-4 (r = 0.927) and TNF-α (r = 0.893) levels." (PMID 32481540, 2020). "Collectively, we uncover DEF6 as player in immune homeostasis ensuring availability of the checkpoint protein CTLA-4 at T-cell surface, identifying a potential target for autoimmune and/or cancer therapy." (PMID 31308374, 2019). "Given the potency of CTLA-4- and PD-1-specific antibodies in improving host immunity and increasing survival in cancer patients, these agents are expected to open a promising avenue to the development of novel medicines for sepsis." (PMID 31636634, 2019). "The PD-1/PD-L1 checkpoint and the CTLA4 checkpoint are the most extensively studied targets for more efficacious and precise cancer immunotherapy, especially in non-small-cell lung cancer (NSCLC)." (PMID 31091813, 2019). "The dual checkpoint blockade, using anti-PD1 and anti-CTLA-4 antibodies, was considered a first combinatorial approach in cancer immunotherapy." (PMID 30853982, 2019). "RNAi experiments followed up by NGS (next generation sequencing) showed that the cancer cells with CTLA4 knocked down gained proliferation advantages." (PMID 31358815, 2019). "Cancer cells were confirmed to release exosomes carrying PD-1, PD-L1 or cytotoxic lymphocyte antigen 4 (CTLA-4)." (PMID 31665020, 2019). "By the end of 2018, as many as 7 types of ICIs have been approved by FDA for the treatment of cancers and all of them were immune checkpoint blockers against PD-1/PD-L1 or CTLA-4." (PMID 31690319, 2019). "In conclusion, anticytotoxic CTLA-4, PD-1/PD-L1 checkpoint inhibitors have a relevant clinical value in a large number of solid tumors, becoming a new pillar in cancer therapy but with an efficacy limited by intrinsic or acquired resistance to these agents." (PMID 31179334, 2019). "Related to this the CTLA-4 mediated signaling in CTLs refers to the negative regulation of T-cell function, which is clearly unfavorable in the case of cancer." (PMID 31191821, 2019).